ARF1 (ARF GTPase 1)
Diseases named in the same sentence as ARF1 in open-access papers (continued):
Sharing a sentence is not in itself a finding about the gene and the disease.
breast carcinoma (continued). "To address whether overexpression of ARF1 is sufficient to confer enhanced invasive capacities of breast cancer cells, we next used the ER+ MCF7 cells characterized as highly proliferative, but non-invasive tumor cells." (PMID 26908458, 2016). "LM11 also inhibited ARF1 activation in breast cancer cells, and this effect was dose dependent." (PMID 27517156, 2016). "To study the relevance of ARF1 in breast cancer, we aimed to examine whether expression of this GTPase was modulated in tissue samples from breast cancer patients." (PMID 26908458, 2016). "On the basis of these clues, we wondered whether ARF1 functions as a metastasis promoter in breast cancer to drive metastasis." (PMID 27517156, 2016). "We next investigated ARF1 expression in human breast cancer tissue of various histological grades." (PMID 26908458, 2016). "Overall, our findings demonstrate that ARF1 is a molecular switch for cancer progression and thus suggest that limiting the expression/activation of this GTPase could help improve outcome for breast cancer patients." (PMID 26908458, 2016). "Interestingly, the levels of active GTP-bound ARF1 were strongly correlated with ARF1 expression in breast cancer cells." (PMID 27517156, 2016). "In the present study, we provide strong evidences that ARF1 is a key protein of breast cancer invasiveness in a murine model and further demonstrate that it could be a potential prognostic factor for patients." (PMID 26908458, 2016). "Interestingly, AMF-26, a small molecule octahydronaphthalene derivative, inhibits ARF1 activation and induces complete regression of human breast cancer BSY-1 xenografts." (PMID 27213581, 2016). "Recently Arf1 has been implicated in the control of cell proliferation, due to its ability to regulate pRB/E2F1 activity and gene expression enhancing proliferation and progression of breast cancer." (PMID 25754106, 2015). "Finally, we examined the presence of ARF1 in a TMA comprising a variety of breast cancer tissues." (PMID 26908458, 2016). "However, whether in an in vivo setting, elevated ARF1 expression, in certain types of breast cancer cells, indeed contributes to tumor invasiveness was unknown." (PMID 26908458, 2016). "Moreover, we revealed the copy number amplification and mRNA overexpression of ARF1, suppression of which could result in the inhibition of breast cancer cell migration and proliferation." (PMID 25137136, 2014). "Specifically focusing on breast cancer (BRCA), RNA-seq data revealed that ARF1 mRNA levels were significantly upregulated in tumor tissues compared to normal breast tissue (p < 0.001)." (PMID 41465279, 2025). "In situ vaccination with Arf1 inhibition was effective not only against melanoma but also against tumors of a variety of histologic types, such as colon cancer (CT26) and breast carcinoma (4T1)." (PMID 31924786, 2020). "LM11 induced cytotoxicity against breast cancer cells (IC50 = 40 μM) and 10 μM of LM11 suppressed Arno-dependent migration, because of its inhibition of Arf1 functions at the Golgi." (PMID 31991585, 2020). "Recently, a novel ARF1- ARFGEF inhibitor AMF-26, which differed structurally from BFA, has shown potential for inducing complete regression of human breast cancer BSY-1 xenografts in vivo." (PMID 27517156, 2016). "To understand how ARF1 contributes to invasiveness, we used a poorly invasive breast cancer cell line, MCF7 (ER+), and examined the effects of overexpressing ARF1 to levels similar to that found in invasive cell lines." (PMID 26908458, 2016). "ARF1 has been found in complex with Grb2 and p66Shc upon EGF stimulation of the basal like breast cancer MDA-MB-231 cell line." (PMID 25890053, 2015). "The small GTPases ARF1 and ARF6 have been shown to be activated downstream of the EGFR and act as key regulator of growth, migration and invasion of breast cancer cells." (PMID 25890053, 2015).
breast carcinoma (continued). "In non-stimulated, highly invasive breast cancer cells, ARF1 is partially localized to dynamic plasma membrane ruffles where epidermal growth factor (EGF) stimulation promotes its rapid and transient activation." (PMID 35805075, 2022). "Interestingly, ARF1 is highly expressed in a variety of malignant tumors 17, 18 and has been reported to activate the ERK pathway in breast cancer." (PMID 33408784, 2021). "We have previously studied Arf1 inhibitors and have shown that LM11 could inhibit cell invasion and suppressed metastasis in breast cancer, as well as Exo2 could inhibit cell migration and invasion in prostate cancer." (PMID 31991585, 2020). "The expression of both ARF1 and ARF6 is up-regulated in the most invasive breast cancer cell lines." (PMID 26908458, 2016). "ARF1 function largely dependents on its activation and LM11, a cell-active inhibitor that specifically inhibits ARF1 activation through targeting the ARF1-GDP/ARNO complex at the Golgi, significantly impairs metastatic capability of breast cancer cell in zebrafish." (PMID 27517156, 2016).
prostate carcinoma (12 papers, 2016 to 2024). A carcinoma that arises from epithelial cells of the prostate gland. "For example, in prostate cancer, we have linked Arf1 to the hyperactivation of mitogen activated protein kinase (MAPK)." (PMID 31991585, 2020). "We found that mutation of Thr48 to Ser impaired the Golgi localization of ARF1 in prostate cancer DU145 and PC3 cells and the mutant ARF1T48S was largely expressed in the cytoplasm." (PMID 27213581, 2016). "To further study the function of ARF1 in prostate cancer cells, we determined the effect of mutating Thr48 on the activation of the MAPK pathway and cell proliferation." (PMID 27213581, 2016). "Our recent studies demonstrating that ARF1 is involved in the activation of the MAPK ERK1/2 pathway which has been implicated in the progression of prostate cancer prompt us to define the possible function of ARF1 in prostate cancer." (PMID 27213581, 2016). "To investigate if increased ARF1 expression was directly linked to ERK1/2 activation in prostate cancer, we determined if manipulating ARF1 expression could alter ERK1/2 activation." (PMID 27213581, 2016). "Recent studies demonstrate that the activation of ARF1, specifically at the GC, directly modulates prostate cancer cell migration and invasion in response to the activation of G protein-coupled receptor (GPCR) CXCR4." (PMID 35805075, 2022). "There are several important points regarding the role of Gβγ, PI3Kγ and ARF1 in mediating ERK1/2 activation by OR51E2 in prostate cancer cells." (PMID 36313302, 2022). "Altogether, these data demonstrate a signaling pathway to mediate ERK1/2 activation by OR51E2 in which Gβγ translocation to the GA induces the activation of PI3Kγ and ARF1, and the GA provides a spatial platform in prostate cancer cells." (PMID 36313302, 2022). "We have recently shown that, in addition to Gβγ and PI3Kγ, ARF1 activation also plays an essential role in ERK1/2 activation by CXCR4 in prostate cancer cells." (PMID 36313302, 2022). "Our data presented here have clearly revealed that Gβγ, PI3Kγ and ARF1 mediate ERK1/2 activation by OR51E2 in prostate cancer cells, which are highly consistent with our previous studies on CXCR4-medited ERK1/2 activation." (PMID 36313302, 2022). "The ADP-ribosylation factor 1 (ARF1) has been reported as significantly elevated in various cancers, and its expression in prostate cancer correlated with activation of ERK1 and ERK2, leading to cell proliferation." (PMID 31805664, 2019). "Activation of small GTPases such as Ras and Arf1 is a critical component of the signaling pathways for most of the receptors shown to be upregulated in advanced prostate cancer." (PMID 28830537, 2017). "Depletion of Arf1 in prostate cancer cells impairs ERK1/2 activation and suppresses cell proliferation in vitro and prostate tumorigenesis in vivo." (PMID 28830537, 2017). "Our previous study has demonstrated that elevated levels of Arf1 in prostate cancer cells positively correlate with hyperactivation of the ERK1/2 MAPK pathway." (PMID 28830537, 2017). "This study bridges two important small GTPases Ras and Arf1 with an emphasis on ERK MAPK signaling in the development of prostate cancer." (PMID 28830537, 2017). "This study suggests that simultaneous blockade of Arf1 and Ras activation in prostate cancer cells is a potential targeted therapeutic strategy for preventing prostate cancer development." (PMID 28830537, 2017). "We show that Exo2, a small-molecule inhibitor that reduces Arf1 activation, effectively suppresses prostate cancer cell proliferation by blocking ERK1/2 activation." (PMID 28830537, 2017). "We then used two different strategies to determine if altered expression of ARF1 correlated with ERK1/2 activation in prostate cancer cells." (PMID 27213581, 2016). "We have demonstrated that ARF1 expression is elevated in human prostate cancer tissues and cells and the expression level of ARF1 is directly correlated with prostate tumorigenesis." (PMID 27213581, 2016).
prostate carcinoma (continued). "Here we have demonstrated that ARF1 expression is significantly elevated in prostate cancer cells and human tissues and that the expression levels of ARF1 correlate with the activation of mitogen-activated protein kinases (MAPK) ERK1/2." (PMID 27213581, 2016). "ARF1 antibody staining of clinic primary prostate tissues and tissue microarray demonstrated that the levels of ARF1 were significantly increased in prostate cancer tissues compared with normal prostate epithelium." (PMID 27213581, 2016). "The number of Ki67-positive cells was markedly reduced in the tumors derived from ARF1 knockdown cells as compared with the tumors derived from the control cells, indicating that ARF1 affects prostate cancer cell proliferation in vivo." (PMID 27213581, 2016). "To directly investigate the role of ARF1 in prostate cancer malignancy, we first determined the short-term effect of increased ARF1 expression on cell proliferation." (PMID 27213581, 2016). "Similar to human prostate cancer tissues, ARF1 expression was also significantly increased in all tested prostate cancer cell lines, including LNCaP, DU145, PC3, 22Rv1, M12 and M2182, as compared to that in the normal prostate P69 and RWPE1 cells." (PMID 27213581, 2016). "We then determined the effect of reducing ARF1 expression on the growth of prostate cancer DU145 and PC3 cells." (PMID 27213581, 2016). "We then determined the effect of shRNA-mediated knockdown of ARF1 on the activation of ERK1/2 in prostate cancer cells in which ARF1 is highly expressed." (PMID 27213581, 2016). "Consistent with the role of ARF1 in regulating ERK1/2 activation, lentiviral expression of ARF1 in normal prostate epithelial cells dramatically enhanced, whereas ARF1 depletion in prostate cancer cells inhibited ERK1/2 activation." (PMID 27213581, 2016). "The function of ARF1 in regulating prostate cancer cell growth is likely mediated through activating the Raf1/MEK/ERK1/2 pathway." (PMID 27213581, 2016). "As an initial approach to study the possible function of ARF1 in prostate cancer, we studied the expression of ARF1 in human prostate cancer tissues by immunohistochemistry." (PMID 27213581, 2016). "The same strategies were used to determine if altered expression of ARF1 correlated with prostate cancer cell growth." (PMID 27213581, 2016). "Based on these findings, we postulate that, in prostate cancer, elevated expression/activation of ARF1 promotes the activation of the Raf1/MEK/ERK1/2 pathway." (PMID 27213581, 2016). "We first determined if activation of endogenous CXCR4 by stromal cell–derived factor 1α (SDF1α) could activate ARF1 in human androgen–insensitive prostate cancer (DU145 and PC3) cells and human embryonic kidney 293 (HEK293) cells." (PMID 34022220, 2021). "Also, the small inhibitor EXO2 reduces ARF1 activation and effectively impairs the proliferation of prostate cancer cells by blocking ERK1/2 activation." (PMID 32426352, 2020). "In prostate cancer, ARF1 promotes tumorigenesis by controlling MAPK activation and cell growth." (PMID 32426352, 2020). "We demonstrate here that the combination of Exo2 and salirasib exhibits a superior anticancer activity in prostate cancer, which is mediated at least in part by suppression of tumor growth through co-inhibition of Arf1- and Ras-mediated MAPK activity in cancer cells." (PMID 28830537, 2017). "Assessment of Arf1 inhibitor efficacy in a preclinical model and evaluation the synergistic anticancer effects of the combination of Arf1 and Ras inhibitors, have immediate potential in reducing cancer morbidity and improving the quality of life of those affected by prostate cancer." (PMID 28830537, 2017). "Additionally, this novel approach to combat prostate cancer by simultaneous blockade of Arf1- and Ras-mediated signaling cascades, has significant impact on the design and execution of effective therapy for prostate cancer patients." (PMID 28830537, 2017).
prostate carcinoma (continued). "We demonstrated that, in parallel with the effects on ERK1/2 activation, ARF1 overexpression in normal prostate cells significantly augmented, whereas ARF1 knockdown in prostate cancer cells markedly attenuated cell growth both in cultured cells in vitro and in the mouse xenograft model in vivo." (PMID 27213581, 2016). "Indeed, ARF1 was found to be highly expressed in several invasive prostate cancer cells and prostate cancer patients." (PMID 27213581, 2016). "The first strategy was to define if enhancing ARF1 expression could increase ERK1/2 activation in normal prostate cells and the second strategy was to determine if reducing ARF1 expression could decrease ERK1/2 activation in prostate cancer cells." (PMID 27213581, 2016). "However, virtually nothing is known about the function of ARF1 in prostate cancer." (PMID 27213581, 2016). "Therefore, similar to the oncogene Ras and the Ras-mediated MAPK pathway, ARF1 and ARF1-mediated ERK1/2 activation may represent novel molecular targets for prostate cancer therapeutics and diagnosis." (PMID 27213581, 2016). "Collectively, our data demonstrate that OR51E2 activates ERK1/2 through the Gβγ-PI3Kγ-ARF1 pathway that occurs spatially at the Golgi, and also provide important insights into MAPK hyper-activation in prostate cancer." (PMID 36313302, 2022). "In summary, we have demonstrated that ectopically expressed OR51E2 is a potent activator of the MAPKs ERK1/2 in prostate cancer cells and that the function of OR51E2 in activating ERK1/2 is mediated through a specific GA-localized Gβγ-PI3Kγ-ARF1 pathway." (PMID 36313302, 2022). "Our data demonstrate that GA-localized ARF1 inhibitors and ARF1 depletion by siRNA and CRISPR–Cas9 remarkably suppress prostate cancer cell migration and invasion induced by activation of CXCR4, an important GPCR involved in prostate cancer metastasis." (PMID 34022220, 2021). "In the current study, we have shown that ARF1 is significantly upregulated in prostate cancer and that manipulation of ARF1 expression is able to control ERK1/2 activation and prostate cancer cell growth." (PMID 27213581, 2016). "As one of the best characterized signaling pathways involved in the progression of prostate cancer, the Raf1/MEK/ERK1/2 pathway is under control by the small GTPase ARF1 which is also upregulated." (PMID 27213581, 2016). "As the first study to elucidate the molecular mechanisms underlying ERK1/2 activation by OR51E2, we focus on three important signaling molecules: Gβγ, PI3Kγ and ARF1, which we have recently demonstrated to control CXCR4-mediated ERK1/2 activation in prostate cancer cells." (PMID 36313302, 2022). "Then, ARF1 stimulates ERK1/2, thus inducing prostate cancer cell migration and invasion." (PMID 35805075, 2022). "These receptors, together with enhanced expression of other signaling molecules, particularly Gγ9 and ARF1, may partially contribute to hyper-activation of oncogenic MAPK pathway in prostate cancer patients." (PMID 36313302, 2022). "We also show that depletion of ARF1 by siRNA and CRISPR–Cas9 and inhibition of GA-localized ARF1 activation abolish ERK1/2 activation by CXCR4 and Gβγ translocation to the GA and suppress prostate cancer PC3 cell migration and invasion." (PMID 34022220, 2021). "Furthermore, the same study shows that the simultaneous blockade of ARF1 and RAS activation in prostate cancer is a potential targeted strategy to prevent the development of this type of tumor." (PMID 32426352, 2020). "LM11 impairs Arf1 activation more strongly than Exo2 in cancer cells; therefore, our follow-up investigations will be focused on studying LM11 efficacy and its potential synergistic effects with salirasib in prostate cancer." (PMID 28830537, 2017). "Interestingly, ARF1 was mainly expressed in the cytoplasm in both P69 and RWPE1 cell lines, whereas it was strongly colocalized with GM130, a Golgi marker, in prostate cancer DU145 and PC3 cells." (PMID 27213581, 2016).
prostate carcinoma (continued). "Thus, we treated DU145 and PC3 cells with Arf1 inhibitors BFA, Secin H3 or Exo2 to explore whether they affect the MAPK pathway in prostate cancer cells." (PMID 28830537, 2017). "The function of ARF1 in prostate cancer has not been investigated." (PMID 27213581, 2016).
microcephaly (7 papers, 2021 to 2025). A congenital or acquired developmental disorder in which the circumference of the head is smaller than normal for the person's age and sex. "Clinical evidence suggests that individuals harbouring variants in the ARF1 gene display a consistent set of phenotypic features, including intellectual disability, microcephaly, epilepsy, and periventricular nodular heterotopia (PVNH)." (PMID 40689678, 2025). "For instance, 14 ARF1 variants have been identified in affected individuals that displayed symptoms including microcephaly, intellectual disability, seizures and periventricular nodular heterotopia." (PMID 38413626, 2024). "Lastly, mutations in the human genes for ARFGEF2 and ARF1 have been associated with cortical malformations, including periventricular nodular heterotopia and microcephaly, indicating that the ARFGEF2-Arf1 pathway is critical for cerebral cortical development." (PMID 37848288, 2023). "For instance, microcephaly has been associated with mutations in RAB3GAP/RAB18, ARFGEF2, ARF1, kinesin KIF2A, or dynein heavy chain, all affecting both membrane trafficking and neuronal morphogenesis." (PMID 39115595, 2024). "Moreover, changes in the regulation of Arf1, such as, for example, those caused by mutations in ARFGAP2 encoding the Arf1 activating protein, manifest in chorea or microcephaly, the symptoms present in ChAc patients and Cohen syndrome patients." (PMID 34830155, 2021).
triple-negative breast carcinoma (6 papers, 2016 to 2025). An invasive breast carcinoma which is negative for expression of estrogen receptor (ER), progesterone receptor (PR), and human epidermal growth factor receptor 2 (HER2). "Notably, Arf1 has been reported to be activated downstream of the EGFR in triple negative breast cancer cells (TNBC) cells." (PMID 31991585, 2020). "Upregulation of ADP-ribosylation factor 1 (ARF1) leads to EMT and resistance to chemotherapeutic agents in triple-negative breast cancer cells." (PMID 37511111, 2023). "In triple negative breast cancer cells (TNBC), we showed that ARF1 controlled mainly the activation of MMP9 and MMP2 through FAK37." (PMID 35680971, 2022).